GPS2 (G protein pathway suppressor 2)
Description:
Key regulator of inflammation, lipid metabolism and mitochondrion homeostasis that acts by inhibiting the activity of the ubiquitin-conjugating enzyme UBE2N/Ubc13, thereby inhibiting 'Lys-63'-linked ubiquitination (By similarity). In the nucleus, can both acts as a corepressor and coactivator of transcription, depending on the context. Acts as a transcription coactivator in adipocytes by promoting the recruitment of PPARG to promoters: acts by inhibiting the activity of the ubiquitin-conjugating enzyme UBE2N/Ubc13, leading to stabilization of KDM4A and subsequent histone H3 'Lys-9' (H3K9) demethylation (By similarity). Promotes cholesterol efflux by acting as a transcription coactivator. Acts as a regulator of B-cell development by inhibiting UBE2N/Ubc13, thereby restricting the activation of Toll-like receptors (TLRs) and B-cell antigen receptors (BCRs) signaling pathways (By similarity). Acts as a key mediator of mitochondrial stress response: in response to mitochondrial depolarization, relocates from the mitochondria to the nucleus following desumoylation and specifically promotes expression of nuclear-encoded mitochondrial genes. Promotes transcription of nuclear-encoded mitochondrial genes by inhibiting UBE2N/Ubc13. Can also act as a corepressor as part of the N-Cor repressor complex by repressing active PPARG. Plays an anti-inflammatory role in macrophages and is required for insulin sensitivity by acting as a corepressor (By similarity). Plays an anti-inflammatory role during the hepatic acute phase response by interacting with sumoylated NR1H2 and NR5A2 proteins, thereby preventing N-Cor corepressor complex dissociation. In the cytosol, also plays a non-transcriptional role by regulating insulin signaling and pro-inflammatory pathways (By similarity). In the cytoplasm, acts as a negative regulator of inflammation by inhibiting the pro-inflammatory TNF pathway; acts by repressing UBE2N/Ubc13 activity (By similarity). In the cytoplasm of adipocytes, restricts the activation of insulin signaling via inhibition of UBE2N/Ubc13-mediated ubiquitination of AKT (By similarity). Able to suppress G protein- and mitogen-activated protein kinase-mediated signal transduction. Acts as a tumor-suppressor in liposarcoma. (Microbial infection) Required for efficient replication of hepatitis C virus (HCV) by promoting the interaction between VAPA and HCV virus protein NS5A.
Synonyms: AMF-1
Tractability: PROTAC: UniProt records ubiquitination sites on it; ubiquitination databases record sites on it; its protein half-life has been measured.
Gene: Protein-coding gene on chromosome 17 (7,311,324 to 7,315,564, reverse strand). Ensembl gene ENSG00000132522.
Subcellular location: Nucleus; Mitochondrion; Cytoplasm, cytosol
Subcellular location (Human Protein Atlas): Nucleoplasm
Pathways (Reactome):
Disease: HCMV Early Events
Gene expression (Transcription): MLL4 and MLL3 complexes regulate expression of PPARG target genes in adipogenesis and hepatic steatosis
Chromatin organization: HDACs deacetylate histones
Metabolism: PPARA activates gene expression
Signal Transduction: NR1H3 & NR1H2 regulate gene expression linked to cholesterol transport and efflux
Gene Ontology:
Molecular function: cyclin binding; protein binding; transcription coactivator activity; transcription corepressor activity; GTPase inhibitor activity; transcription coregulator activity
Biological process: negative regulation of JNK cascade; negative regulation of transcription by RNA polymerase II; positive regulation of cholesterol efflux; positive regulation of transcription by RNA polymerase II; B cell differentiation; JNK cascade; negative regulation of B cell receptor signaling pathway; negative regulation of fat cell differentiation; negative regulation of inflammatory response; negative regulation of protein K63-linked ubiquitination; negative regulation of toll-like receptor signaling pathway; negative regulation of tumor necrosis factor-mediated signaling pathway; positive regulation of peroxisome proliferator activated receptor signaling pathway; regulation of fat cell differentiation; regulation of lipid metabolic process; regulation of transcription by RNA polymerase II; response to mitochondrial depolarisation
Cellular component: cytosol; mitochondrion; nucleoplasm; nucleus; transcription repressor complex; transcription regulator complex; cytoplasm
Genetic constraint (gnomAD): Loss-of-function variants: 22 observed, 48.7 expected, observed/expected ratio (o/e) 0.45, 90% interval 0.32 to 0.64. The synonymous counts are far from expectation, so gnomAD's model fits this gene poorly and the ratio says little. Missense variants: 366 observed, 408.01 expected, observed/expected ratio (o/e) 0.9, 90% interval 0.82 to 0.98. Synonymous variants: 202 observed, 141.16 expected, observed/expected ratio (o/e) 1.43, 90% interval 1.27 to 1.61.
Homologues: Orthologues: chimpanzee GPS2 (100% identical), macaque GPS2 (99% identical), dog GPS2 (98% identical), guinea pig GPS2 (98% identical), pig GPS2 (98% identical), rabbit GPS2 (98% identical), mouse Gps2 (98% identical), rat Gps2 (91% identical), zebrafish gps2 (60% identical), tropical clawed frog gps2 (34% identical), Drosophila melanogaster CG17002 (26% identical).
Diseases named in the same sentence as GPS2 in open-access papers:
GPS2 is named in the same sentence as 44 diseases in open-access papers, as found by Europe PMC text mining. Sharing a sentence is not in itself a finding about the gene and the disease. The quoted sentences say what the papers report.
breast carcinoma (8 papers, 2017 to 2025). "We previously reported that GPS2 deletion in triple-negative MDA-MB231 breast cancer cells is associated with the upregulation of MYC and MYC-dependent target genes." (PMID 40305047, 2025). "GPS2 has recently been identified as a significantly mutated gene in breast cancer and other malignancies and proposed to work as a putative tumor suppressor." (PMID 33490071, 2020). "Together these results demonstrated that loss of GPS2 promotes activation of AKT kinase in breast cancer cells, in vitro and in vivo, similarly to what previously reported in adipocytes." (PMID 33490071, 2020). "Collectively, these observations confirm a tumor suppressor role for GPS2 and reveal that loss of GPS2 promotes breast cancer cell proliferation and tumor growth through uncontrolled activation of AKT signaling." (PMID 33490071, 2020). "In addition, G protein pathway suppressor 2 (GPS2) is a significantly mutated gene in breast cancer, medulloblastoma and other tumors." (PMID 34419139, 2021). "Our results indicate that GPS2 deletion in MCF-7 breast cancer cells leads to increased HDAC3 ubiquitination and dismissal from most of its genomic locations, including both repressed and activated gene targets." (PMID 40305047, 2025). "GPS2 depletion in breast cancer cells results in sustained PI3K/Akt signaling and increased cell proliferation, migration and invasion, which can be inhibited by MK2206." (PMID 34419139, 2021). "As Ubc13 overexpression was reported to promote breast cancer metastasis through aberrant activation of a TAK1/p38 MAPK kinase cascade, it is possible, for example, that loss of GPS2 regulates cell proliferation and migration through complementary pathways." (PMID 33490071, 2020). "Moreover, our study points to GPS2 as a potential biomarker for a subclass of breast cancers that would be responsive to PI3K-class inhibitor drugs." (PMID 33490071, 2020). "Depletion of GPS2 in MDA-MB-231 cells in fact correlates with an increase in proliferation, migration and invasion in vitro, and increased tumor burden with elevated cell proliferation in an in vivo xenograft mouse model of breast cancer." (PMID 33490071, 2020). "Here, we investigated the role of G-Protein Pathway Suppressor 2 (GPS2), a transcriptional cofactor critical for maintaining cellular homeostasis via regulation of mitochondrial biogenesis, stress response, lipid metabolism, insulin signaling, and inflammation, in MCF-7 breast cancer cells." (PMID 40305047, 2025).
Obesity (7 papers, 2019 to 2025). Accumulation of substantial excess body fat. "In humans with obesity, reduced G protein pathway suppressor 2 (GPS2) expression in macrophages causes elevated systemic and adipose tissue inflammation, insulin resistance, and diabetes." (PMID 33679598, 2020). "The decrease in GPS2 expression in adipocytes is closely associated with obesity." (PMID 34419151, 2021). "Moreover, the authors used palmitate as obesity-linked metabolic trigger of inflammation and observed that Gps2-deficient macrophages had an elevated pro-inflammatory gene signature." (PMID 33117357, 2020). "Vice-versa, transplantation of Gps2-overexpressing bone marrow into two mouse models of obesity reduced inflammation and improved insulin sensitivity in recipient mice." (PMID 33117357, 2020). "We further explored the role of hepatocyte GPS2 in obesity-induced liver steatosis and insulin resistance." (PMID 30975991, 2019). "Our studies have particularly revealed that SMRT and GPS2 depletion sensitizes mouse macrophages to pro-inflammatory stimuli, consistent with correlation analysis of human adipose tissue macrophages in the context of obesity and type 2 diabetes." (PMID 36610795, 2023). "Our study underscores the novel finding that Gps2 expression may play a pivotal role in mediating the DHA-induced intracellular signaling pathways’ modulation and emphasizes the importance of considering the adipocyte maturation stage in anti-obesity strategies." (PMID 37686130, 2023).
medulloblastoma (3 papers, 2014 to 2021). A malignant, invasive embryonal neoplasm arising from the cerebellum. "Among others, mutation of the GPS2 (G-protein Pathway Suppressor 2) gene was identified as a potential driver in both settings, in agreement with similar observations reported from genomic profiling of other cancer cohorts, including pan-cancer metastatic solid tumors and medulloblastomas." (PMID 33490071, 2020).
steatosis (3 papers, 2019 to 2023). Increased lipid within the cytoplasm of cells. "Hepatocyte-specific Gps2 knockout in mice alleviates the development of diet-induced steatosis and fibrosis and causes activation of lipid catabolic genes." (PMID 30975991, 2019). "Moreover, activation of PPARα ameliorates liver fibrosis and inhibits the function of hepatocyte-specific G-protein pathway suppressor 2 (GPS2), alleviating the development of diet-induced steatosis and fibrosis and causing activation of lipid catabolic genes." (PMID 38004166, 2023).
triple-negative breast carcinoma (3 papers, 2020 to 2025). An invasive breast carcinoma which is negative for expression of estrogen receptor (ER), progesterone receptor (PR), and human epidermal growth factor receptor 2 (HER2). "Here, we have profiled the phenotypic changes induced by GPS2 depletion in MDA-MB-231 triple negative breast cancer cells and investigated the underlying molecular mechanisms." (PMID 33490071, 2020). "Here, we have investigated GPS2 role as a tumor suppressor in the context of triple negative breast cancer and provide evidences that loss of GPS2 promotes cell proliferation and tumor growth through sustained AKT activation." (PMID 33490071, 2020). "It has been reported that GPS2 deletion activates AKT signaling to promote proliferation of triple-negative breast cancer cells (MDA-MB-231), and it inhibits the proliferation of gastric cancer cells by increasing the ubiquitylation of the epidermal growth factor receptor (EGFR)." (PMID 38755610, 2024). "To begin investigating the function of GPS2 as a tumor suppressor in triple negative breast cancer, we generated two MDA-MB-231-GPS2 knockout lines by CRISPR-Cas9 genome editing with two independent sets of sgRNA." (PMID 33490071, 2020).
viral infection (3 papers, 2020 to 2025). "Western blotting results showed that virus infection caused the degradation of GPS2, and the protein level of GPS2 in the cytoplasm bulk increased when virus-infected cells were treated with MG132." (PMID 33658351, 2021). "Collectively, these data clearly demonstrated that the degradation of GPS2 protein caused by viral infection was related to NEP-mediated nuclear export." (PMID 33658351, 2021). "Conversely, GPS2-KO-down-regulated genes were enriched in protein transport, response to viral infection, and cell differentiation." (PMID 40305047, 2025). "Analysis of the changes in GPS2 protein level after virus infection showed that the protein level of GPS2 decreased in the WSN H1N1- and DW H5N1-infected A549 cells in a dose-dependent manner." (PMID 33658351, 2021). "With respect to the salivary gland barrier, only CPR1- or GPS2-CP binding were reported to facilitate viral infection in the salivary glands." (PMID 32817722, 2020). "Thus, the subcellular localization of host protein GPS2 in the presence of NEP or virus infection required investigation." (PMID 33658351, 2021).
gastric cancer (2 papers, 2022 to 2024). A primary or metastatic malignant neoplasm involving the stomach. "These potentially new gastric cancer driver genes, as well as genes with high nonclonal mutation frequency, such as STK11, GPS2, NDUFB9, and AXIN2, represent good candidates for inclusion in future studies of gastric tumorigenesis." (PMID 36970058, 2022).
hepatoma (2 papers, 2013 to 2020). "For example, SUMOylation of the human LRH-1 K224, the lysine residue corresponding to mouse LRH-1 K289, binds to a transcriptional co-repressor complex consisting of NCOR1, HDAC3 and G Protein Pathway Suppressor 2 (GPS2) in hepatoma cells." (PMID 32370667, 2020). "Knockdown of GPS2 in hepatoma cell lines suppressed the replication of HCV RNA, which can be rescued by the expression of an RNAi-resistant GPS2." (PMID 24223774, 2013).
liposarcoma (2 papers, 2016 to 2020). A usually painless malignant tumor that arises from adipose tissue. "To explore the roles of GPS2 in regulation of biological characteristics of liposarcoma cells, we checked the effect of loss of GPS2 on proliferation, migration, and apoptosis of SW872 cells in vitro." (PMID 27460081, 2016). "GPS2 has also been reported to function as a tumor suppressor in liposarcoma, in agreement with predictive analyses from genome sequencing data." (PMID 33490071, 2020). "To explore the potential role of GPS2 in liposarcomas, we collected 14 LPS samples and their paired normal adipose tissues." (PMID 27460081, 2016). "Overall, our results have confirmed that GPS2 functions as a tumor suppressor, as previously suggested by multiple evidences from genomic profiling of human cancer biopsies and by in vitro data from liposarcoma." (PMID 33490071, 2020).
melanoma (2 papers, 2021 to 2024). A malignant, usually aggressive tumor composed of atypical, neoplastic melanocytes. "In addition, GPS2 expression is reduced in a variety of tumors (such as osteosarcoma and melanoma) and adipose tissues, indicating that GPS2 is closely related to tumor cell proliferation and lipid-associated inflammation." (PMID 38755610, 2024).
non-alcoholic steatohepatitis (2 papers, 2019 to 2023). "GPS2, a subunit of the NCoR and HDAC3 complex, plays a crucial role in the progression of non-alcoholic steatohepatitis (NASH)." (PMID 37674539, 2023). "Here we demonstrate that G protein pathway suppressor 2 (GPS2), a subunit of the nuclear receptor corepressor (NCOR) and histone deacetylase 3 (HDAC3) complex, has a central role in these alterations and accelerates the progression of NAFLD towards non-alcoholic steatohepatitis (NASH)." (PMID 30975991, 2019).
prostate carcinoma (2 papers, 2023). A carcinoma that arises from epithelial cells of the prostate gland. "The tumor suppressor features of miRNA-642 was also confirmed by an alteration of expression of potential target genes, such as WT1, NUAK1, RASSF3, SKP2, GPS2 and IGFBP3, in prostate cancer." (PMID 37108073, 2023).
chronic hepatitis C (1 paper, 2013). "Further studies to elucidate the precise roles of GPS2 and its interaction with NS5A in HCV replication should provide valuable insights into viral host interaction and development of novel therapeutics for chronic hepatitis C." (PMID 24223774, 2013).
colorectal cancer (1 paper, 2025). A primary or metastatic malignant neoplasm that affects the colon or rectum. "Preoperative GPS2 is an independent poor prognostic factor in patients with colorectal cancer and synchronous peritoneal metastases, and surgical resection does not improve prognosis in patients with GPS2." (PMID 40607290, 2025).
Hepatic fibrosis (1 paper, 2023). The presence of excessive fibrous connective tissue in the liver. "Specifically, under methionine-deficient and choline-deficient (MCD) diet conditions, GPS2-knockout mice showed reduced activities of AST and ALT, decreased hepatic steatosis, and improved hepatic fibrosis, thereby preventing the development of NAFLD and other associated disorders." (PMID 38004166, 2023).
Hepatic steatosis (1 paper, 2019). Steatosis is a term used to denote lipid accumulation within hepatocytes. "As a result of loss of PPARα repression, Gps2 LKO mice showed alleviated liver steatosis upon HFD feeding and improved fibrosis upon MCD feeding, due to increased lipid burning as detected by elevated ketone body levels." (PMID 30975991, 2019). "Here the authors show that GPS2 inhibits PPARα activity and that ablation of GPS2 ameliorates hepatic steatosis in mice." (PMID 30975991, 2019). "While Gps2 LKO resulted in improved liver steatosis and reduced lipid accumulation, Ncor LKO resulted in the opposite." (PMID 30975991, 2019). "Through diet-induced mouse models of fatty liver disease along with next-generation sequencing analysis we provide evidence that Gps2 ablation improved liver steatosis and fibrosis, which correlated with the selective activation of lipid catabolic genes." (PMID 30975991, 2019). "As these data collectively suggest that GPS2 promotes the progression of fatty liver disease via antagonizing PPARα, the selective therapeutic modulation of GPS2–PPARα interactions could be of interest for future disease interventions." (PMID 30975991, 2019). "Remarkably, the protective phenotype of the Gps2 LKO mice is unique amongst hitherto described coregulator KO mouse models in the context of NAFLD as it is the only model which improved diet-induced fatty liver disease instead of worsening it (for references, see Introduction)." (PMID 30975991, 2019).
human papillomavirus infection (1 paper, 2021). "In previous studies, GPS2 could be degraded in the cells under human papillomavirus infection or other stimuli." (PMID 33658351, 2021).
Impaired glucose tolerance (1 paper, 2022). An abnormal resistance to glucose, i.e., a reduction in the ability to maintain glucose levels in the blood stream within normal limits following oral or intravenous administration of glucose. "GPS2-deficient mice fed an HFD presented a state of increased systemic inflammation and impaired glucose tolerance, suggesting that GPS2 levels negatively correlate with systemic and AT inflammation." (PMID 36499659, 2022).
latent infection (1 paper, 2023). "The expression of several factors implicated in the inhibition of viral transcription elongation, such as PCF11 (4.3-fold), GPS2 (2.6-fold), HEXIM1 (3.7-fold), and HEXIM2 (2.7-fold), was significantly upregulated in latent infection compared to actively infected cells." (PMID 38038477, 2023).
leukemia (1 paper, 2020). A malignant (clonal) hematologic disorder, involving hematopoietic stem cells and characterized by the presence of primitive or atypical myeloid or lymphoid cells in the bone marrow and the blood. "In addition, dysregulation of C4A, and GPS2, are also known to be involved in the development of leukemia in humans when they are dysregulated." (PMID 33195511, 2020).